MIR6819 (microRNA 6819)
Synonyms: hsa-mir-6819
Gene: MicroRNA gene on chromosome 22 (36,286,847 to 36,286,907, reverse strand). Ensembl gene ENSG00000278420.
Homologues: Orthologues: chimpanzee MIR6819 (100% identical).
Diseases named in the same sentence as MIR6819 in open-access papers:
MIR6819 is named in the same sentence as 1 disease in open-access papers, as found by Europe PMC text mining. Sharing a sentence is not in itself a finding about the gene and the disease. The quoted sentences say what the papers report.
tumor (1 paper, 2024). "Patients #5, #6, and #7 (without tumor samples) showed an overlap of four genes (SORL1, PTPRC, MIR6819, and NAMPT), while #6 and #7 also shared five genes (CELF2, EDEM3, SMCHD1, RAVER1, and CXCR1)." (PMID 39001407, 2024).